DDR1 (discoidin domain receptor tyrosine kinase 1)
Diseases named in the same sentence as DDR1 in open-access papers (continued):
Sharing a sentence is not in itself a finding about the gene and the disease.
tumor (continued). "Dasatinib, nilotinib, a DDR1 blocking antibody, the selective DDR1 inhibitors 7rh and DDR1-IN-1 and the selective allosteric DDR2 inhibitor WRG-28 were shown to efficiently prevent DDR-mediated tumor progression in preclinical models." (PMID 32793493, 2020). "In fact, our study is first to show that DDR1 is essential for TIC growth and TIC-derived tumor formation." (PMID 33173221, 2020). "Our data indicates that DDR1 signaling is a major source of AKT and ERK phosphorylation in tumor cells." (PMID 32090682, 2020). "In this tumor context, we provide evidence that LRP-1 regulates by endocytosis the cell surface levels of DDR1 expression." (PMID 32582700, 2020). "Collagen also signals to cells through the receptor tyrosine kinases discoidin domain receptors DDR1 and DDR2; both of them have also been reported to interact with type I collagen and to play a role in tumor progression." (PMID 32426274, 2020). "DDR1-IN-1 decreased total MMP2 and total MMP9 (mainly detected as pro-MMPs and active MMPs) secretion by basal HSCs and tumor-activated-HSCs." (PMID 33110221, 2020). "Together with the data obtained using DDR1-IN-1, these results indicate that AKT and ERK phosphorylation rates, MMP9 expression and tumor cell proliferation are modified by DDR1 signaling and/or by DDR1 expression." (PMID 32090682, 2020). "First, it will be important to clarify DDR1 and DDR2 respective roles in CRC, specifically in the stromal and tumor compartments." (PMID 32117772, 2020). "The fact that DDR1 expression level is not restricted to any specific CMS subclass and that its tumor-promoting function is KRAS mutation-independent suggests that DDR1 inhibitors could be active in all CRC subtypes, including CMS3 tumors for which the therapeutic options are limited." (PMID 32117772, 2020). "In order to assess if the identified kinases in the invasion assay correlate with expression levels in tumors from GC patients, mRNA and protein expression levels for FRK, DDR1, SIK2 and SRC were assessed in tumor samples from GC patients." (PMID 32082487, 2020). "The upregulation of miR-486-3p exhibited a tumor suppressor activity by inhibiting tumor growth and inducing apoptosis, by targeting the 3’-UTR of Discoidin domain receptor-1 (DDR1)." (PMID 33369458, 2020). "We then showed that nilotinib can inhibit the DDR1‐mediated invasive potential of CRC cells in a liver metastasis mouse model and of patient‐derived cell lines originating from metastatic tumours and circulating CRC cells." (PMID 29438985, 2018). "Our results also suggest that, by dampening DDR1‐dependent β‐catenin activity in CRC, nilotinib reduces tumour cell dissemination and prevents their capacity to target distant organs in patients with CRC." (PMID 29438985, 2018). "Accumulating evidences also showed that DDR1 functioned as an inducer of MMP2 and MMP9, which contributed to matrix components degradation during tumor invasion." (PMID 28743276, 2017). "Across a cohort of 30 patients, we examined DDR1 expression in paired PDAC and corresponding adjacent non-tumor tissues by real-time quantitative PCR (RT-qPCR), or western blotting." (PMID 26297342, 2015). "DDR1 expression was correlated significantly with both AJCC/UICC stage (r = 0.45, p = 0.03) and tumor status (r = 0.42, p = 0.04) in patients." (PMID 20799954, 2010). "Consistent with recently published findings and our results indicating a critical role for DDR1 in HCC progression, we found a significant correlation between the expression of DDR1 and AJCC/UICC tumor stage." (PMID 20799954, 2010). "Motivated by compelling evidence of DDR1’s role in shaping immunosuppressive PDAC microenvironments, we therapeutically targeted DDR1 using a novel neutralizing antibody (HYXL-3) to assess blockade efficacy in reversing immune evasion and inhibiting tumor progression." (PMID 40869052, 2025). "Notably, DDR1 also modulates immune responses within the TME, playing a key role in tumor immune evasion." (PMID 41154598, 2025).
tumor (continued). "GO and KEGG enrichment analyses of Differentially expressed genes (DEGs) identified through DDR1-based stratification demonstrated significant enrichment in immune-related signaling pathways, suggesting DDR1 contributes to PDAC tumor biology via immunomodulatory mechanisms." (PMID 40869052, 2025). "In thyroid cancer, DDR1 knockdown increases the expression of thyroid differentiation markers (NIS, Tg, TSH, TPO) while decreasing epithelial-mesenchymal transition (EMT) markers and tumor cell stemness." (PMID 40563472, 2025). "In severely immunodeficient NSG mice bearing subcutaneous KPC PDAC tumors, treatment with the DDR1-neutralizing antibody alone did not significantly inhibit tumor growth compared to human IgG1-Fc controls." (PMID 40869052, 2025). "In addition, the expression of PD1 on tumor-infiltrating CD8 + T cells increased after CIR and rose further upon combined DDR1 inhibition." (PMID 40993737, 2025). "Furthermore, the synergistic use of DDR1 degraders with chemotherapy, other targeted therapies, or immunotherapy (including cell-based therapies) could improve treatment efficacy by sensitizing tumors to therapeutic agents, disrupting the tumor microenvironment, and reinstating immune responses." (PMID 40713963, 2025). "Further multialgorithm analyses revealed that elevated DDR1 expression is significantly correlated with immune cell infiltration in NSCLC, which may play a crucial role in tumor promotion and immune escape." (PMID 41394854, 2025). "Conversely, blue shading represents negative CRISPR log-fold change scores, implying that DDR1 knockout enhances lymphocyte-mediated tumor killing." (PMID 40869052, 2025). "DDR1/2 inhibition augments CD4+ and CD8+ T-cell infiltration through the suppression of IL-18 synthesis while reducing ECM stiffness, thereby prolonging the survival of tumor-bearing mice." (PMID 39799341, 2025). "Finally, a therapeutic DDR1 blockade in a KPC PDAC mouse model remodeled the collagen scaffold, restored antitumor immunity, and curtailed tumor growth." (PMID 40869052, 2025). "However, future studies should focus on the mechanisms by which DDR1 activation accelerates and the HGF–MET axis decelerates HCC tumor growth." (PMID 40248197, 2025). "For example, DDR1 modulates the MMP and chemokine secretion to recruit macrophages, shaping an immunosuppressive TME, a mechanism validated in hepatic metastasis models where DDR1 silencing reduces MMP2/9 and prometastatic factors in HSCs, thereby inhibiting tumor growth and immune escape." (PMID 41394854, 2025). "Discoidin domain receptor 1 (DDR1) is a collagen-binding receptor tyrosine kinase (RTK) that preserves extracellular matrix (ECM) homeostasis and, consequently, influences tissue repair, fibrosis, and tumor progression." (PMID 40869052, 2025). "However, after DDR1 knockdown, tumour growth was inhibited, and HOXA6 overexpression reversed the action of DDR1 silencing." (PMID 40105492, 2025). "Together, these findings indicate that DDR1 promotes aggressive tumor traits such as angiogenesis, EMT, and stemness in a cancer type–specific manner, while simultaneously downregulating cell death and DNA repair pathways in select tumor contexts." (PMID 40869052, 2025). "Collectively, these findings could position DDR1 as a driver of tumor progression and therapy resistance by mediating immune evasion in HNSCC, thereby providing a rationale for targeting DDR1 to restore antitumor immunity and enhance therapeutic outcomes." (PMID 40993737, 2025). "Nevertheless, Ddr1‐KD did not impact tumor growth in CAFs co‐injecting nude mice, whereas it inhibited tumor growth in CAFs co‐injecting immunocompetent C57 mice." (PMID 38953306, 2024). "This aligns with our previous findings that DDR1 did not affect the proliferation of tumor cells in vitro." (PMID 38953306, 2024).
tumor (continued). "We propose that by designing a multistage responsive nanomedicine with tunable sizes, carrying DDR1‐siRNA and SN38, enabling tumor ECM active modulation, softening the tumor and blocking cancer cell signaling to overcome MMDR in CRC and achieve a synergistic chemo‐immunotherapy effect." (PMID 38953306, 2024). "DDR1 is a non-integrin receptor that binds fibrillar collagens, and its activation has been found in metastatic tumor populations." (PMID 38907027, 2024). "Simultaneously, tumor‐infiltrating total and activated (CD44hiCD62Llo) CD8+ and CD4+ T cells, were more abundant in Ddr1‐KD tumors, indicating a negative correlation between intratumoral tumor infiltrating lymphocytes (TILs) abundance and DDR1 expression." (PMID 38953306, 2024). "Importantly, western blot analysis showed that LA-conditioned PCa cells, upregulating DDR1 expression, when seeded on LA-induced tumor decellularized ECM, exhibit both higher DDR1 and STAT3 phosphorylation/activation." (PMID 38907027, 2024). "Analysis of the tumor weight 60 days after s.c.injection revealed a higher weight of the tumor masses derived from CAF and lactate scrambled tumor xenografts compared to both DDR1 and P4HA1-silenced counterparts, although not statistically significant." (PMID 38907027, 2024). "Downregulation of DDR1 triggers TGFBI secretion and tumor progression." (PMID 36906534, 2023). "Next, we evaluated the pathway through which DDR1 may involve by using GSEA analysis, in 33 tumor types from TCGA." (PMID 37031216, 2023). "To investigate whether DDR1 knockout altered immune cell infiltration into the TME, we created tumor single-cell suspensions and performed staining for a lymphoid flow cytometry panel." (PMID 38136314, 2023). "Indeed, studies have identified multiple effects of DDR1 and DDR2 on tumor growth and metastasis when expressed on tumor and CAFs." (PMID 37662958, 2023). "Moreover, at the tumor level, TRPV4 gene expression was lower in the more aggressive fusion+ than in fusion− tumors, opposite to the DDR1 expression trend." (PMID 35957513, 2022). "Although inhibition of DDR1 reduces the growth of mouse PDAC24, the ability of DDR1 to control tumour metabolism by stimulating macropinocytosis and mitochondrial biogenesis was unknown." (PMID 36198801, 2022). "Anti-DDR1-ECD monoclonal antibody resulted in fewer and shorter arrangements of collagen fibers at the tumor edge, which enhanced immune cell infiltration, increased the total number of infiltrating CD8+ and CD4+ T cells, and promoted interferon gamma (IFN-γ) production." (PMID 35935941, 2022). "Thus, the link between tumor aggressiveness, collagen III and V, and DDR1 should be further explored." (PMID 35957513, 2022). "Finally, to understand the impact of DDR1 and collagen I on tumor development and aggressiveness in RMS patients, we compared the overall survival of patients with high and low DDR1 gene‐expressing tumors." (PMID 35957513, 2022). "Other targets of miR-199a that may affect tumor proliferation and metastasis are ROCK1, HIF1α, BCAM, FZD6, and DDR1." (PMID 36499729, 2022). "A recent study showed targeting DDR1 as a therapeutic strategy against resistance to BRAF and MEK inhibitors, further confirming the significance of our findings, which suggest an unprecedented role of the interactome of DDR1, BCR, and ABL1 proteins with EGFR-ERBB2-4 signaling in tumor progression." (PMID 35664781, 2022). "We thus propose that treatments that target DDR1–IKKβ–NF-κB–NRF2 signalling and mitochondrial biogenesis should be evaluated in prospective clinical trials that include stromal state—an important modifier of tumour growth—as an integral biomarker." (PMID 36198801, 2022). "We therefore conducted a comparative investigation of targeting DDR1 in combination with EGFR inhibitor (lapatinib), utilizing an additional tumor model of GBM and including the brain penetrable DDR1/BCR-ABL inhibitor nilotinib to evaluate its combinatorial efficacy." (PMID 35664781, 2022).
tumor (continued). "In this study, we also investigated whether DDR1 affects the downstream pathways, and found that DDR1 shRNA or miR-199b-5p could significantly suppress ERK signalling in PCa cells and xenograft tumours." (PMID 33239676, 2021). "Also in TNBC, co-expression of DDR1 and Protein phosphatase 1 regulatory subunit 1B (PPP1R1B, also known as DARPP-32) inhibits tumor cell migration." (PMID 34805157, 2021). "Anlotinibalso suppresses tumor growth by blocking c-Kit, RET, Aurora-B, c-FMS, and DDR1." (PMID 34421608, 2021). "More and more articles report the involvement of DDR1 and/or DDR2 in cancer and tumor invasion." (PMID 35004699, 2021). "Furthermore, knockdown of AKT3 increased the activity and phosphorylation of pro-metastatic HER2 and DDR1/2 but lowered protein levels of CTGF after TGFβ-stimulation, an axis involved in tumor-induced osteolysis." (PMID 33670586, 2021). "DDR1 is not important for tumor initiation, but it is critical in early tumor development and progression in KRAS (Ki-ras2 Kirsten rat sarcoma viral oncogene homolog)-driven lung adenocarcinoma." (PMID 33917302, 2021). "Tumor-activated KCs secretomes, but no basal KCs secretomes, enhanced C26 proliferation rate, which was reverted by DDR1-IN-1." (PMID 33110221, 2020). "In contrast, CYR61 and AXL levels were not increased in +DDR1/+COL1 tumours when compared to −DDR1/+COL1 tumours." (PMID 32047176, 2020). "Tumor secretomes enhanced DDR1 protein expression by ~ 1.4 fold in KCs, while it did not modify DDR1 protein levels in HSCs or LSECs." (PMID 33110221, 2020). "Finally, we identified a new molecular way that controls the cell-surface expression of DDR1 and suggested an additional role of LRP-1 as a key sensor of the tumor microenvironment." (PMID 32582700, 2020). "On the other hand, DDR1-IN-1 reduced the induction of C26 proliferation by tumor-activated HSCs, but it did not affect significantly C26 migration." (PMID 33110221, 2020). "Both DDR1 and DDR2 were shown to promote tumor cell proliferation, survival, and migration." (PMID 32793493, 2020). "DDR1 staining is more evident in samples with ALI than those without, whereas PDPN expression is uniquely localized in the invasion front or outward regions of ALI positive tumor sections." (PMID 32244515, 2020). "Interestingly, EMT was reported to rely on the switch from DDR1 (epithelial) to DDR2 (mesenchymal) expression, although various reports implicate both DDR1 and DDR2 in EMT-mediated tumor cell invasion." (PMID 32793493, 2020). "Further, knockdown of Ddr1 suppresses the growth of TICs and TIC-derived tumor growth in mice." (PMID 33173221, 2020). "Although on basis of these and similar findings in other tumor entities, DDR1 emerges as a promising novel target to interfere with tumorigenicity, an explicit involvement of DDR1 in the process of CAM-DR is experimentally still lacking." (PMID 32668815, 2020). "How exactly and in which circumstances DDR1 and DDR2 may regulate human tumor evasion, particularly in CRC, deserve further investigation." (PMID 32117772, 2020). "Levels of FRK, DDR1 and SRC expression on both mRNA and protein level were significantly higher in metastatic patient samples regardless of the tumor stage, while expression levels of SIK2 correlated with tumor size." (PMID 32082487, 2020). "In the present work, we investigated whether LRP-1 may control DDR1 expression at the plasma membrane in non-invasive CRC and influence its ability to regulate tumor cell proliferation upon its activation by type I collagen." (PMID 32582700, 2020). "Basal-SCs or tumor activated-SCs monocultures were treated or not with DDR1-IN-1 and collagen I (see “Material and methods”)." (PMID 33110221, 2020). "Ddr1 knockdown in TICs significantly attenuated TIC-derived tumor growth to one third of that with TICs with Scr-sh, supporting the functional role of DDR1 in tumor development." (PMID 33173221, 2020).
tumor (continued). "Under those conditions, DDR1 gene expression was enhanced in HSCs and KCs in response to the tumor secretomes, but not in LSECs." (PMID 33110221, 2020). "DDR1 and DDR2 have been demonstrated to predominantly regulate tumor progression." (PMID 31130862, 2019). "In non-tumor sections these proteins are either not expressed (DDR1 and SPCA2) or faintly expressed (Orai1 and Kv10.1), suggesting the importance of their simultaneous expression to sustain the aggressiveness and the resistance of the tumor." (PMID 30718673, 2019). "Finally, we examined DDR1 invasive activity and its inhibition by nilotinib in patient‐derived CRC cell lines we recently generated from metastatic tumours and circulating CRC cells in blood samples." (PMID 29438985, 2018). "We also found that DDR1 inhibition reduced DDR1 activation, EMT, and tumor growth." (PMID 28143619, 2017). "In a multivariate analysis, DDR1 expression was not a predictor of poor overall survival; however, old age, being male, having an undifferentiated tumor, and advanced T stage were all significant factors of poor survival." (PMID 28143619, 2017). "To evaluate whether DDR1 expression is required for tumor cell growth in vivo, we examined the effect of DDR1 knockdown on the growth of BXPC3 tumor xenografts in mice." (PMID 25369402, 2014). "Recombinant TGFBI was capable of inhibiting tumor cell growth in vitro as well as wound healing in a similar manner although there was no change in DDR1 expression." (PMID 25369402, 2014). "In conclusion, our study not only adds more clarity to how DDR1 may be mediating tumorigenesis, but also supports the tumor suppressor role of TGFBI and suggests that TGFBI may serve as a biomarker for modulators of DDR1." (PMID 25369402, 2014). "We observed that DDR1 and TGFBI expression is reciprocal in several tumor cell lines." (PMID 25369402, 2014). "The mechanisms by which DDR1 affects signaling cascades involved in tumor progression, invasion, and metastasis have not yet been fully characterized." (PMID 21541037, 2011). "Analyzing predictive factors for advanced tumor stage at the time of HCC diagnosis, we found a positive correlation between AJCC/UICC stage III-IV and poor tumor differentiation, presence of macrovascular invasion, and high DDR1 expression." (PMID 20799954, 2010). "Multivariate analysis revealed DDR1 is an independent favourable predictor for prognosis independent of tumour differentiation, stage, histology, and patient age." (PMID 17299390, 2007). "As ECM stiffness generally regulates tumor progression through its receptors, we systematically screened several common ECM-sensing receptors (ITGB1, CD44, Piezo1, Piezo2, YAP1, Syndecan1, and DDR1) via siRNA knockdown, and confirmed the knockdown efficiency by conducting qRT-PCR analyses." (PMID 40685383, 2025). "As a result, these inhibitors are prone to resistance and fail to address the immunosuppressive effects mediated by DDR1’s extracellular non-enzymatic domain, limiting their efficacy in achieving complete tumor regression within the complex tumor microenvironment." (PMID 40713963, 2025). "This hypothesis was confirmed by the data collected in this study, which showed that DDR1 inhibition increased the radiosensitivity of CIR, specifically manifesting in the suppression of HNSCC cell proliferation and the delay of tumor growth in syngeneic MOC1 subcutaneous tumor models." (PMID 40993737, 2025). "However, DDR1 knockdown significantly reduced GSH levels and GPX4, SLC7A11 and ZEB1 expression and increased MDA and Fe2+ levels, as well as ACSL4, E‐cadherin, p‐YAP and p‐NF2 expression levels in tumour tissues." (PMID 40105492, 2025).